MDM2 (MDM2 proto-oncogene)
Diseases named in the same sentence as MDM2 in open-access papers (continued):
Sharing a sentence is not in itself a finding about the gene and the disease.
tumor (continued). "There was a lower age (48.8 ± 1.63 vs. 54.5 ± 1.24 years, p = 0.007), more females (21/51 vs. 12/52, p = 0.049), larger tumor sizes (16.79 ± 4.03 vs. 6.63 ± 1.15 cm3, p = 0.018) and more invasive behavior (28/51 vs.16/52, p = 0.013) in high MDM2 patients than in low MDM2 patients." (PMID 36837574, 2023). "Overexpressed MDM2 attenuated tumor growth suppression by S100A6." (PMID 37217945, 2023). "The activation of the Jak-STAT pathway in tumor cells after PD-1 antibody treatment could stimulate MDM2 expression and induce treatment resistance." (PMID 37333017, 2023). "have shown that microRNA loci are frequently involved in tumor cell proliferation, migration, and invasion and contribute to direct inhibition and MDM2-mediated destabilization of FOXO1, suggesting that FOXO1 inhibition may be interested in HCC development." (PMID 38057816, 2023). "This demonstrated that MDM2 can act as an oncogene, a gene that can promote tumor development." (PMID 37297833, 2023). "MDM2 is indeed overexpressed in 40–60% of human sarcomas as well as many other solid and hematologic malignancies, making it a very attractive target for anti-tumor drugs." (PMID 37175549, 2023). "Immunohistochemically, the tumor tested positivity for MDM2, CDK4, and p16." (PMID 37881487, 2023). "Hyperactivation of tumor-promoting genes such as MYC and MDM2 is associated with OS tumorigenesis." (PMID 37511127, 2023). "Although it needs to be confirmed in a larger series of patients, we suggest that MDM2 expression might be used as a predictive biomarker of tumor response to ILP, thus improving the selection of patients who can best benefit from this treatment." (PMID 38138884, 2023). "Additionally, MDM2 can act as an oncogene itself by promoting tumor cell survival and promoting cell growth and proliferation." (PMID 37297833, 2023). "We further explored the biological significance of MDM2 in the tumor-promoting function of NAT10." (PMID 36609449, 2023).
tumor (continued). "Overexpression of MDM2 could modulate various proangiogenic pathways and induce tumor angiogenesis in several tumors, including gastric cancer, breast carcinoma, prostate cancer and ovarian carcinoma." (PMID 36837574, 2023). "Consequently, it can be determined that MDM2 is a tumor prognostic gene for LGG after studying its prognostic value and survival time." (PMID 37049742, 2023). "An axillary test for the presence of MDM2 amplification in cell-free DNA may help verify the results of a traditional tumor biopsy, or may be useful if the results of tumor biopsy are equivocal or uninterpretable." (PMID 34986184, 2022). "The MDM2 inhibitor Navtemadlin arrests mouse tumor growth and potentiates radiotherapy." (PMID 36922937, 2022). "Furthermore, the anti‐tumour efficacy of MDM2 inhibitor RG7388 was also evaluated as a single‐agent therapy or in combination with the first‐line chemotherapeutic in different models." (PMID 35692096, 2022). "Moreover, we report a strong synergistic effect of combined pharmacological inhibition of MDM2 and eIF2α, resulting in a rapid apoptotic response in vitro and halted tumor growth and host survival in vivo." (PMID 36456590, 2022). "Multiple red signal clusters could be seen in the tumor cells of all tissues, suggesting MDM2 amplification in primary tumor and PDXs tissues." (PMID 35928724, 2022).
tumor (continued). "Moreover, after silencing SNHG1 alone, tumor growth was repressed, and after overexpressing MDM2 alone, tumor growth was promoted." (PMID 36230661, 2022). "MDM2 is a proto-oncogene commonly overexpressed in tumour cells." (PMID 35486574, 2022). "Notably, this set contained several activated DEGs from sets of those found with cells producing uS10mut1, uS10mut2, or uS10mut3, including tumor-associated genes such as GADD45A, PPM1D, MDM2, and CREBRF." (PMID 35682850, 2022). "A study analyzed the somatic alterations with next generation sequencing of tumor tissue in HPDs treatment with ICIs in advanced solid tumors and showed that copy number alterations in MDM2/MDM4, EGFR, and several genes located on 11q13 were associated with HPD." (PMID 35399666, 2022). "In addition, we observed that tumours with RS4 had an increased frequency of SVs in genomic regions containing MDM2, H3F3B, PTPRB and GRM3 compared to tumours devoid of RS4." (PMID 35396535, 2022). "Furthermore, inhibition of MDM2 phosphorylation leads to cell apoptosis and cell cycle arrest, thus repressing tumor cell proliferation in esophageal cancer cells." (PMID 35875060, 2022). "In the context of cell cycle regulation and apoptosis, we hypothesize that the HMA-resistant cells evade apoptosis not only by PTEN suppression but also by MDM2 downregulation, with both PTEN and MDM2 functioning as tumor suppressors." (PMID 35628480, 2022). "If confirmed in a larger series, our data suggest that an ancillary non-invasive test for amplification of MDM2 and other DDLPS-associated genes in cell-free DNA may help with the pre-operative diagnosis when imaging or tumor biopsy is equivocal." (PMID 34986184, 2022). "We therefore proceeded with investigating whether there is a link between the effects of 5-ISA-fortified extract and the epigenetic regulation of tumor suppressor genes by RB/MDM2 pathway." (PMID 36296971, 2022). "Patients with MDM2 overexpression and immunosuppressive tumor microenvironment may have the largest benefit from the use of USP7 inhibitors." (PMID 36428632, 2022). "Moreover, in this group, overexpression was found in several tumor oncogenic genes (such as CCND1, MDM2, MDM4, and DNMT3A), which positively associated with hyperprogression, which led to ICB-related high progression of the disease." (PMID 35909893, 2022).
tumor (continued). "In sum, ZLM-7 could inhibit MDM2 expression via 14-3-3 sigma and thus inhibited tumor growth in vivo." (PMID 35890172, 2022). "PDX models established in this study can be used for biology research and new treatment evaluation of RLPS, especially for preclinical studies that target MDM2 amplification, adipogenesis process, tumor blood vessel or vessel formation, and CAFs and TAMs infiltration." (PMID 35928724, 2022). "MDM2 is abnormally upregulated in several types of tumours, especially those of mesenchymal origin." (PMID 36601599, 2022). "An in vivo study of the MDM2 inhibitor showed significant anti-tumor activity in DDLPS mice." (PMID 36555969, 2022). "Treatment with SJ-172550 combined with MDM2 inhibitors additively suppresses tumor growth." (PMID 35454137, 2022).
tumor (continued). "Moreover, the identification of MDM2 amplification in the tumor further helped us to make the diagnosis." (PMID 36059611, 2022). "Overexpression of MDM2 abrogated the effect of silencing SNHG1 on tumor growth." (PMID 36230661, 2022). "Treatment with MDM2 inhibitor RG7112 significantly suppressed tumor growth of DDLPS PDX in mice." (PMID 35928724, 2022). "In addition, NMD inhibition also inhibits tumor growth in a MDM2-overexpressing xenograft tumor model." (PMID 34481841, 2021). "MDM2 had a relatively low but stable expression among multiple organ systems according to the results from the GTEx dataset in our study, and it was significantly highly expressed in the tumor tissues of ccRCC patients (TCGA dataset)." (PMID 33850477, 2021). "Hence, studies have shown that combination therapy using MDM2/MDMX inhibitors result in a more effective anti-tumor reaction by more actively inducing apoptosis and cancer cell cycle arrest." (PMID 34307171, 2021). "The activation of AKT has been involved in nuclear translocation of MDM2 in tumor cells." (PMID 34298892, 2021). "Rescue experiments validated miR-1252-5p mimics, or CCNE2/MDM2 short hairpin RNA could reverse the hsa_circ_0000073 overexpressing-induced impairment of malignant tumor behavior." (PMID 34568326, 2021). "MDM2 target genes were enriched for those involved in serine, glycine, glutamine, and cysteine metabolism, and serine or glycine deprivation increased MDM2 chromatin binding at target genes to sustain serine/glycine biosynthesis and promote tumor growth." (PMID 34532654, 2021).